TSHR (thyroid stimulating hormone receptor)
Diseases named in the same sentence as TSHR in open-access papers (continued):
Sharing a sentence is not in itself a finding about the gene and the disease.
thyroid cancer (continued). "We analyzed TSHR expression in the clinicopathological features of thyroid cancer." (PMID 37208644, 2023). "Collectively, these results demonstrated that the constructed nanoparticles finely encapsulated 131I in PLGA nanoparticles, and rhTSH was absorbed on the surface of the 131I-PLGA-rhTSH nanoparticles, which served as a selective guide for TSHR-expressing thyroid cancer." (PMID 36776316, 2023). "Therefore, our findings not only contribute to the understanding of TSHR/ETE/EMT regulation in thyroid cancer but also provide a rationale for exploring the targeting of autophagy as a novel therapeutic strategy for this disease." (PMID 38174330, 2023). "Many literatures have reported that thyroid cancer cell lines lost TSHR expression." (PMID 37208644, 2023). "TSHR is also an important protein that regulates the occurrence and development of thyroid cancer and is therefore a potential target for the diagnosis and treatment of thyroid cancer." (PMID 38111381, 2023). "The reasons for this phenomenon may be multifaceted, including, but not limited to, enhancing the selective binding of rhTSH to TSHR-expressing thyroid cancer cells." (PMID 36776316, 2023). "Furthermore, the normal expression and function of TSHR was essential for the character of thyroid cancer cells and the prognosis of patients with an RAIR status." (PMID 37208644, 2023). "Moreover, the methylation level of TSHR was significantly higher in the thyroid cancer tissue compared to adjacent normal tissue." (PMID 36013156, 2022). "In this study, we developed a CAR-T therapy for TSHR-positive advanced thyroid cancers." (PMID 35252208, 2022). "We first constructed several TSHR-targeting CARs for the treatment of advanced thyroid cancers." (PMID 35252208, 2022). "Finally, our studies have shown the efficacy of TSHR CAR-T cells in the treatment of TSHR-positive thyroid cancers." (PMID 35252208, 2022). "In addition to targeting specific thyroid cancer cells, other markers like galectine-3 or TSHR can, possibly, be investigated as potential targets for cancer imaging." (PMID 33926024, 2021). "It has also been reported that TSHR upregulation promotes the apoptosis of thyroid cancer cells." (PMID 34804362, 2021). "To test our hypothesis that PTEN/PI3K signaling is involved in crosstalk with the TSHR pathway in thyroid cancer cells, we first knocked down PTEN, the key regulator of PI3K signaling, by siRNA-mediated transfection in TPC1 and BCPAP cells." (PMID 34650915, 2021). "Utility of thyroid-specific mRNA transcripts such as thyroid peroxidase (TPO), sodium-iodide symporter (NIS), thyroglobulin (TG), and thyroid stimulating hormone receptor (TSHR) in predicting thyroid cancer recurrences and metastases had been assessed previously using whole blood." (PMID 34512731, 2021). "We subsequently investigated whether TSH could further stimulate the expression of thyroid genes in thyroid cancer cells since TSHR plays an important role in up‐regulating iodide‐handling genes in thyroid cells." (PMID 31970877, 2020). "Dedifferentiation of thyroid cancer may lead to the decreased expression of TSHR and diminished signal transduction after TSHR activation." (PMID 32300552, 2020). "Nevertheless, clinically, the expression levels of TSHR seem to be downregulated in patients with more advanced stages of thyroid cancer, especially for those with poorly differentiated cell types, suggesting the existence of an uncharacterized selection/adaption mechanism." (PMID 32698392, 2020). "Also, small molecule antagonist to the TSHR would offer yet another approach to inhibit thyroid cancer progression by suppressing TSHR signalling." (PMID 32472423, 2020). "Considering the stability and easily manufactured nature of protein or peptidyl drugs, it may be more reasonable to develop antagonists of TSHR to avoid systemic side effects, while manifesting effectiveness to inhibit thyroid cancer growth." (PMID 32698392, 2020).
thyroid cancer (continued). "However, the first report suggesting TSHR mRNA as a blood biomarker of thyroid cancer was published back in 2002, and more recently the clinical usefulness of TSHR mRNA has been questioned." (PMID 30781659, 2019). "However, as a novel biomarker, circulating TSHR-mRNA for thyroid cancer diagnosis have been conducted in limited studies." (PMID 28036261, 2017). "In recent years, there have been many reports of TSHR-mRNA in the diagnosis of thyroid cancer." (PMID 28036261, 2017). "Similarly, in thyroid-specific knock-in of BRAFV600E LSL-Braf(V600E)/TPO-Cre) mouse model in which mice develop aggressive PTC, crossing of these mice with TSHR−/− mice blocked the development of thyroid cancer." (PMID 28117293, 2017). "TSHR may avoid malignant transformation of thyroid cells and suppress the occurrence of thyroid cancer, but it may promote the growth and progression of thyroid cancer once it has been initiated by oncogenic modifications." (PMID 28117293, 2017). "The pooled OR in our study indicated that TSHR had an important role in thyroid cancer." (PMID 28926589, 2017). "The latest article shows that TSHR-mRNA is a molecular marker of thyroid cancer cells circulating." (PMID 28036261, 2017). "An AUC of 0.8427 showed that circulating TSHR-mRNA may be a promising biomarker to discriminate thyroid cancer patients from benign thyroid nodules individuals, with a summary sensitivity of 72% and specificity of 83%." (PMID 28036261, 2017). "According to these observations, screening of mutations in different oncogenes related to thyroid cancer and the role of TSHR mutations in transformation was not well established." (PMID 28117293, 2017). "The performance of TSHR-mRNA for thyroid cancer diagnosis was evaluated in this study." (PMID 28036261, 2017). "Epigenetics has shown to play an integral part in the role of TSHR in thyroid carcinoma." (PMID 28117295, 2017). "It is still uncertain whether this supports TSHR’s role in the initiation of thyroid carcinoma or it is simply due to the TSHR-dependent generation of thyroid cells from which carcinogenesis initiates." (PMID 28117295, 2017). "However, in thyroid carcinomas with a poor response to TSH and high basal adenylate cyclase activity, mutations in TSHR and Gs were reported in 12% of FTC and in 13% of PTC." (PMID 28117293, 2017). "That a silenced TSHR is often present in the case of undifferentiated thyroid cancers is certainly consistent with the existence of endogenous growth or regulatory factors that are alternatives to TSH and may support thyroid tumor cell proliferation." (PMID 25292307, 2015). "Given the limited information concerning the implication of genes involved in the thyroid function on thyroid cancer risk, in this study, we have analysed the risk association between common genetic variants in the THRA, THRB and TSHR genes and DTC in a large Spanish population." (PMID 23781307, 2012). "In conclusion, this study confirms the association of THRA with thyroid cancer in a Spanish population, and it supports the lack of association of TSHR with thyroid cancer as previously reported." (PMID 23781307, 2012). "While epigenetic silencing of TSHR in thyroid carcinomas has been reported, two other studies have shown a lack of association of TSHR polymorphisms with thyroid cancer risk." (PMID 23781307, 2012). "Activating mutations of the TSH receptor (TSHR) or of the gene encoding the Gsα subunit of the heterotrimeric G protein that couples TSHR to adenylyl cyclase (GSP) have been described in 30% of autonomously functioning thyroid adenomas while they are rare in thyroid carcinomas." (PMID 22927847, 2012). "Furthermore, correcting abnormal gene expression in tumor cells is a trend in targeted therapy for tumors, and the successful application of liposomes for mRNA and siRNA delivery has made nanomaterial-based gene editing for regulating TSHR possible in thyroid cancer therapy." (PMID 40532044, 2025).
thyroid cancer (continued). "Recent studies have indicated that TSHR plays a critical role in the progression of thyroid cancer and may serve as a key target for the treatment of residual or metastatic thyroid cancers, particularly radioiodine-refractory differentiated thyroid cancer (RAIR-DTC)." (PMID 40532044, 2025). "Similarly, autoantibodies against TSHR in Graves’ disease are not widely recognized as a risk factor for thyroid cancer development." (PMID 39061242, 2024). "In addition to regulating the TSHR/cAMP signaling pathway, other pathways may also be involved in the redifferentiation of thyroid cancer by SH." (PMID 36142613, 2022). "Furthermore, BANCR/TSHR signaling overexpression can significantly inhibit the luteolin antitumor impacts on thyroid cancer in vivo and in vitro and, as a result, can act as an essential anticancer agent for thyroid cancer through suppressing the BANCR/TSHR pathway." (PMID 33805687, 2021). "Furthermore, they found that miRNA-106a directly targeted RARß and could regulate NIS and TSHR expression and RAI uptake in thyroid cancers, suggesting miRNA-106a as a new diagnostic and therapeutic target." (PMID 33995657, 2021). "Furthermore, we show that STIM1-KD increases the susceptibility of thyroid cancer ML-1 cells to drugs used for treatment of thyroid cancer, reinstates the expression of thyroid stimulating hormone receptor (TSHR), thyroid specific proteins and increased iodine uptake." (PMID 34155535, 2021). "Moreover, we also found that miRNA-106a-RARB could regulate the expression of NIS, TSHR and alter the iodine uptake function of thyroid cancer cells through MAPK signaling pathway." (PMID 27342319, 2016). "Therefore, targeting TSHR is an optimal method to induce the redifferentiation of poorly differentiated carcinoma of the thyroid and increase the iodide uptake of iodine-refractory thyroid carcinomas by increasing the NIS expression." (PMID 26985248, 2016). "Regarding the association of TSHR with thyroid cancer, none of the two genetic variants of TSHR included in our study (rs8019570 and rs11845164) modified the susceptibility to DTC significantly, suggesting a lack of influence of these polymorphisms on the development of DTC." (PMID 23781307, 2012). "In thyroid cancer and gliomas, the TSH-TSHR regulatory axis, particularly high TSHR expression, has been found to facilitate immune evasion by tumor cells." (PMID 40532044, 2025). "TSHR suppresses thyroid cancer cell invasion and metastasis by inhibiting epithelial–mesenchymal transition (EMT) in thyroid cancer cells." (PMID 40532044, 2025). "We also found increased TSHR and NKX2.1 mRNA levels in the 6-month-old mice, which contrasts with studies in human thyroid cancers reporting that the expression of thyroid differentiation genes is unchanged, decreased or lost." (PMID 40004107, 2025). "Thyroid differentiation-related genes (TG, TSHR, and PAX8) were upregulated in PTC-Epis and downregulated in ATC-Epis, which revealed a potential dedifferentiation process in thyroid cancer progression." (PMID 38478516, 2024). "The current research about the incidence, metastasis, and prognosis of thyroid cancer indicated that PIK3CA, PTEN, CDKN1B, TSHR, and EIF1AX were also involved, which should be considered in the multi-gene panel." (PMID 39600648, 2024). "Control experiments validated the impact of SAHA on NIS, TSHR, AP2A1 and PICALM mRNA in thyroid cancer cells." (PMID 37921808, 2024).
thyroid cancer (continued). "Thyroid-stimulating hormone receptor (TSHR), mRNA has been studied as a thyroid cancer marker in pre-surgery diagnosis, detecting malignancy in indeterminate FNA results, monitoring thyroid cancer recurrence, and predicting tumor aggressiveness." (PMID 37547301, 2023). "Considering the coherent correlation between KCNJ16 and TSHR expression and their tendency to decline in tumor tissues, we focused on the potential role of KCNJ16 in thyroid cancer." (PMID 37208644, 2023). "To find out the optimal co-stimulatory domain for thyroid cancer treatment, we compared the in vitro anti-tumor functions of CD28 and 4-1BB-based TSHR CAR-T cells." (PMID 35252208, 2022). "We examined methylation of TSHR, PTEN, and RASSF1A in 20 thyroid cancer tissue samples and compared it to adjacent normal tissue." (PMID 36013156, 2022). "Our research group used bioinformatics to analyze the Oncomine database and found that HT-related genes (TSHR, BACH2, RNASET2, CTLA4, PTPN22, IL2RA) were expressed in different types of thyroid cancer." (PMID 34993154, 2021). "Among them, TSHR and RNASET2 were highly expressed in malignant tumors, especially TSHR in thyroid cancer, while BACH2, CTLA4, PTPN22, IL2RA, and other immune-related genes are expressed significantly lower in thyroid cancer." (PMID 34993154, 2021). "Thyroid-specific genes, including thyroid-stimulating hormone receptor (TSHR), sodium/iodide symporter (NIS), thyroperoxidase (TPO) and thyroglobulin (TG), are downregulated in thyroid cancer." (PMID 34155535, 2021). "They indicated that the suppression of PVT1 causes cell cycle arrest at G0/G1 phase and significantly decreases cyclin D1 expression, thyroid stimulating hormone receptor (TSHR) expression, and the proliferation of thyroid cancer cells in ATC cell line." (PMID 32760219, 2020). "The study showed that BANCR can be recruited by EZH2 to increase the expression level of thyroid-stimulating hormone receptor (TSHR) and promote the proliferation of IHH-4 thyroid cancer cells." (PMID 32596158, 2020). "In a previous study, PVT1 was reported to promote the proliferation of thyroid carcinoma cells by recruiting EZH2 and mediating TSHR expression." (PMID 32596158, 2020). "High levels TSHR signaling requires to upregulate NIS expression and iodide uptake in differentiated thyroid cancer cells." (PMID 30760304, 2019). "ATC lacks most markers seen in thyroid cancer such as thyroglobulin, TTF1, NIS, and TSHR, except PAX8 that can be present consistently in squamous variant ATC but in only 50% of ATC with spindle cell features." (PMID 31835496, 2019). "The main mechanism of RAI-refractory thyroid cancer is the abnormal silencing of NIS and TSHR gene in the thyroid cancer cells." (PMID 30337961, 2018). "PVT1 modulated thyroid cancer cell proliferation by recruiting EZH2 and regulating thyroid-stimulating hormone receptor." (PMID 29046366, 2017). "Thyroid mRNAs such as Tg, TSHR, TPO mRNA has been widely used to detect recurrence or metastasis of thyroid carcinoma as this mRNA showed good sensitivity and specificity for DTC." (PMID 26244057, 2015). "Studies investigating the expression levels of TSHR in thyroid cancer cell lines have revealed that many of these cell lines no longer express TSHR but instead resemble undifferentiated thyroid carcinoma." (PMID 40532044, 2025). "The thyroid stimulating hormone receptor (TSHR) mRNA could detect the presence of thyroid nodules and was utilized for predicting the rate of recurrence in thyroid cancer." (PMID 37091783, 2023). "Next, we evaluated the expressions of thyroid transcription factor (TTF)-1 and − 2 as well as the expression of differentiation related genes, such as thyroid stimulating hormone receptor (TSH-R), thyroglobulin (TG) and sodium/iodide symporter (NIS) in thyroid cancer cell lines." (PMID 37684566, 2023).
thyroid cancer (continued). "Well-differentiated thyroid cancer exhibits active radioactive iodide uptake owing to the appropriate expression of iodide-handling genes, including sodium-iodide symporter (NIS), thyroid peroxidase (TPO), and thyroid-stimulating hormone receptor (TSHR)." (PMID 33499100, 2021). "This body of evidence has not, however, been examined in thyroid cancer cells for the possibility that TSHR and αvβ3 traffick together in these cells when T4 binds to the integrin." (PMID 34234745, 2021). "It would appear worthwhile for the trafficking of the integrin and TSHR to be studied concurrently in thyroid cancer cells in the presence and absence of T4." (PMID 34234745, 2021). "Moreover, RasGRP3 mutation led to the promotion of cell proliferation, migration, and invasion, whereas NIS and TSHR expression and RAI uptake declined through AKT activation in thyroid cancer cells." (PMID 33995657, 2021). "Differentiated thyroid cancer (DTC) cells may lose NIS expression and iodine uptake, but usually express TSH receptors (TSHR)." (PMID 33926024, 2021). "The thyroid-specific genes TSHR, PAX-8, and NIS were significantly upregulated, and improved RAI uptake was noted, whereas expression of CD97, an undifferentiation marker, declined in dedifferentiated thyroid cancers." (PMID 33995657, 2021). "The authors finally proposed that PVT1 may contribute to pathogenesis of thyroid cancer through EZH2 recruitment and TSHR expression regulation." (PMID 32760219, 2020). "This relationship supports the theory that TSHR silencing is a secondary genetic event in thyroid carcinogenesis and not essential for the initiation of thyroid carcinoma." (PMID 28117295, 2017). "Stimulation of TSHR by TSH secreted in the pituitary gland increases the synthesis of H2O2, which is the substrate of thyroperoxidase in thyroglobulin iodination and thyroid hormone synthesis, contributing to the high level of oxidative stress in thyroid cancer patients." (PMID 39180118, 2024). "We agree with the current opinion that TSHR mutations (except for those found at a high level) and/or NIS overexpression do not raise the probability of thyroid cancer or a pre-cancerous tumor, noninvasive follicular thyroid neoplasm with papillary-like nuclear features (NIFTP)." (PMID 30319546, 2018). "However, it is not clearly demonstrated if THSH-TSHR signaling is essential for the initiation of thyroid cancer or if it is required for the TSHR-dependent generation and growth of oncogene-stimulated thyroid cancer cells." (PMID 28117293, 2017). "Titles and abstracts were preliminarily reviewed and a total of 55 articles were excluded for various reasons (including literature type is review, case reports and letter, or studies do not solely focus on TSHR-mRNA and/or not specifically pertain to thyroid cancer)." (PMID 28036261, 2017). "TSHR-Abs are known to stimulate the same intracellular signal pathways as TSH, which has mitogenic and antiapoptotic effects on thyroid follicular cells and thus may play a role in thyroid cancer initiation." (PMID 25421041, 2014). "Indeed, the role of TSHR in thyroid cancer is not clear; however, it is a major thyroid autoantigen, and genetic variants in the TSHR gene have been described to be associated with the risk of thyroid diseases." (PMID 23781307, 2012). "Another issue with using TSHR mRNA to detect thyroid cancer is that its presence in the bloodstream does not entirely reflect its expression in thyroid tissue, as the thymus, pituitary gland, kidney, heart, and retro-orbital tissues also reportedly express TSHR mRNA." (PMID 37547301, 2023). "The XTC-UC1 cell line derived from metastatic Hǔrthle cell carcinoma retains the expression of TSHR and other differentiation markers, but it is less widely used because of its genetic instability and metabolic characteristics, which may not accurately represent broader thyroid cancers." (PMID 40532044, 2025).